VWC2L (von Willebrand factor C domain containing 2 like)
Description:
May play a role in neurogenesis. May play a role in bone differentiation and matrix mineralization.
Tractability: Antibody: UniProt places it where antibodies can reach, with medium confidence; UniProt predicts a signal peptide or a membrane-spanning region; its Gene Ontology location is reachable by antibodies, with medium confidence.
Gene: Protein-coding gene on chromosome 2 (214,411,054 to 214,578,976, forward strand). Ensembl gene ENSG00000174453.
Subcellular location: Secreted; Synapse
Gene Ontology:
Molecular function: protein binding
Biological process: negative regulation of BMP signaling pathway
Cellular component: AMPA glutamate receptor complex; extracellular region; synapse
Genetic constraint (gnomAD): Loss-of-function variants: 10 observed, 22.91 expected, observed/expected ratio (o/e) 0.44, 90% interval 0.27 to 0.74. The upper end of that interval is the gene's LOEUF score, 0.74, which puts it in group 3 of 6, group 1 being the genes least tolerant of losing a copy. Missense variants: 209 observed, 290.64 expected, observed/expected ratio (o/e) 0.72, 90% interval 0.64 to 0.81. Synonymous variants: 96 observed, 98.84 expected, observed/expected ratio (o/e) 0.97, 90% interval 0.82 to 1.15.
Homologues: Orthologues: chimpanzee VWC2L (100% identical), macaque VWC2L (100% identical), pig VWC2L (99% identical), mouse Vwc2l (99% identical), guinea pig VWC2L (98% identical), rat Vwc2l (98% identical), tropical clawed frog vwc2l (89% identical), rabbit VWC2L (83% identical), dog VWC2L (82% identical), zebrafish vwc2l (80% identical). Paralogues in human: VWC2 (51% identical), VWF (28% identical), CHRDL2 (27% identical), MUC5B (27% identical), OTOG (26% identical), CHRDL1 (25% identical), OTOGL (25% identical), MUC5AC (25% identical), FCGBP (24% identical), MUC2 (23% identical), TECTA (23% identical), KCP (23% identical), and 7 more.
Diseases named in the same sentence as VWC2L in open-access papers:
VWC2L is named in the same sentence as 2 diseases in open-access papers, as found by Europe PMC text mining. Sharing a sentence is not in itself a finding about the gene and the disease. The quoted sentences say what the papers report.
pancreatic cancers (1 paper, 2023). "miRNA-143-5p has been implicated in the pathophysiology of cancer (including colon and pancreatic cancers) and schizophrenia-related disorders, and its effects on various target genes, such as EMC2, VWC2L, THY1, SGCZ, HIF1, and JDP2, among others, have been described." (PMID 37179125, 2023).
VWC2L also shares sentences with these, for which no sentence is quoted: cancer (1 paper).